CACNA1A (calcium voltage-gated channel subunit alpha1 A)
Diseases named in the same sentence as CACNA1A in open-access papers (continued):
Sharing a sentence is not in itself a finding about the gene and the disease.
migraine (111 papers, 2005 to 2026). "The rs10405121 variant of the CACNA1A gene showed distinct genotype distributions between migraine patients and controls." (PMID 40869402, 2025). "The pathophysiology of migraine aura is intrinsically connected to genetic factors, particularly mutations in the CACNA1A gene, which encodes the alpha-1 subunit of the CaV2.1 calcium channel." (PMID 39997646, 2025). "Hemiplegic migraine, a severe form of migraine with additional neurological symptoms like paralysis, is also associated with CACNA1A variants." (PMID 40111503, 2025). "Variants in these genes, including CACNA1A, have been associated with rare subtypes of migraine, such as familial hemiplegic migraine, where mutations alter cortical excitability and predispose individuals to CSD." (PMID 40869402, 2025). "The association of the CACNA1A gene with migraine is the subject of ongoing research, with new genetic variants in this gene regularly reported in the literature." (PMID 40869402, 2025). "Given the combination of cerebellar atrophy and a family history of migraine or hemiplegic migraine, investigation into a possible mutation in the CACNA1A gene was explored." (PMID 38785745, 2024). "In migraine, genetic changes in CACNA1A are associated with familial hemiplegic migraine, characterized by aura symptoms and temporary paralysis." (PMID 38785745, 2024). "FHM1 is a monogenic form of migraine mainly characterized by prominent motor deficits during the aura and it is associated with missense CACNA1A variants." (PMID 39110218, 2024). "Genetic variants of CACNA1A have been shown to increase calcium influx and excitatory synaptic transmission, contributing to migraine pathogenesis." (PMID 39684844, 2024). "The CACNA1A gene, responsible for encoding the alpha-1 subunit of the CaV2.1 calcium channel, holds significant importance in discussions surrounding migraine genetics." (PMID 38785745, 2024). "A recent study has identified a polymorphism in the FHM1 CACNA1A gene as a susceptibility locus for common varieties of migraine, among 122 other loci." (PMID 36800925, 2023). "Previous attempts at determining key genes in migraine-associated vertigo suggest the involvement of ion channel genes, such as CACNA1A, ATP1A2, and SCN1A." (PMID 37107589, 2023). "Hautakangas and colleagues found a risk variant in CACNA1A that seemed to be specific for migraine with aura, and stated that “CACNA1A seems involved in both monogenic and polygenic forms of migraine”." (PMID 35785356, 2022). "FHM1 is a monogenic subtype of migraine with aura caused by specific missense mutations in the CACNA1A gene that encodes the pore-forming α1A subunit of neuronal CaV2.1 voltage-gated calcium channels." (PMID 35323663, 2022). "The study found three lead variants associated with migraine with aura, in which one of them, CACNA1A—related to both monogenic and polygenic forms of migraine—provides a gene-based connection between migraine sub-types." (PMID 35910262, 2022). "FHM1 is a monogenic migraine form characterized by motor deficits during the aura and is typically associated with gain-of-function CACNA1A variants." (PMID 33544220, 2021). "We have previously identified a patient with a de novo missense mutation in CACNA1A (p.Y1384C), characterized by hemiplegic migraine, cerebellar atrophy and developmental delay." (PMID 33557884, 2021). "Hemiplegic migraine (HM) is a rare form of migraine, defined by headache associated with transient hemiplegia, and can be caused by mutations in either CACNA1A, ATP1A2, or SCN1A." (PMID 34135856, 2021). "FHM1/SHM1 is a rare migraine with an aura subtype caused by CACNA1A variants, which is characterized by hemiparesis and occasionally encephalopathy during migraine attacks." (PMID 33425808, 2020). "Familial hemiplegic migraine type 1 (FHM1) is a form of migraine with aura caused by heterozygous mutations in 4 genes: CACNA1A, ATP1A2, SNC1A and PRRT2, but further heterogeneity is expected." (PMID 30167989, 2018).
migraine (continued). "One Mendelian form of migraine–familial hemiplegic migraine type 1 (FHM1)–results from gain-of-function missense mutations in human CACNA1A, which encodes the α1 subunit of CaV2.1 (P/Q)-type calcium channels." (PMID 30080864, 2018). "Prior research has demonstrated that gain-of-function mutations in a gene important for neurotransmission (CACNA1A) cause migraine in humans." (PMID 30080864, 2018). "Familial hemiplegic migraine type 1 (FHM1) is a rare monogenic subtype of migraine with aura caused by mutations in CACNA1A that encodes the α1A subunit of voltage-gated CaV2.1 calcium channels." (PMID 27032388, 2017). "Several neurological disorders including familial hemiplegic migraine type 1 (FHM1), a rare monogenic form of migraine with aura, are caused by mutations in the CACNA1A gene, which encodes for the α1A pore-forming subunit of CaV2.1 channels." (PMID 25741235, 2015). "Familial Hemiplegic Migraine type 1 (FHM-1) is a rare monogenic subtype of migraine caused by missense mutations in the CACNA1A gene, which encodes the α1 subunit of CaV2.1 (P/Q-type) Ca2+ channels." (PMID 23326332, 2013). "We report a patient presenting with migraine with aura and cerebellar signs and symptoms, carrying the p.Arg583Gln mutation in the CACNA1A gene." (PMID 22527033, 2012). "In familial hemiplegic migraine (FHM), a rare subtype of migraine with aura, mutations in the CACNA1A gene (localised at C19p13) have been found (FHM1)." (PMID 16162291, 2005). "The identification of three novel CACNA1A variants (ch19:13228374 G > C, ch19:13228428 G > C, and ch19:13228348 A > T) may enhance our understanding of the gene’s role in migraine pathophysiology." (PMID 40869402, 2025). "Our study aims to explore this connection by investigating genetic variants of the CACNA1A gene, with the goal of identifying specific alterations that may contribute to migraine susceptibility and enhancing our understanding of its molecular mechanisms." (PMID 40869402, 2025). "In contrast to those with high concussion tolerance, a mild head impact can cause devastating injury in people with familial hemiplegic migraine (FHM) type 1, an autosomal dominant form of migraine with aura caused by gain-of-function mutations in the calcium channel gene (CACNA1A or Cav2.1)." (PMID 41024271, 2025). "The identification of CACNA1A variants strengthens the hypothesis that migraine may be a channelopathy." (PMID 40869402, 2025). "Therefore, our findings should be considered within the context of broader physiological mechanisms, and future studies should investigate the links between CACNA1A variants, migraine, and vascular traits." (PMID 40869402, 2025). "Studies investigating whether sex modifies the relationship between mutations in the CACNA1A gene and migraine have shown that female sex hormones enhance susceptibility to CSD." (PMID 38674378, 2024). "Although we report on a single patient, this case sets a precedent which may support a trial with this effective therapy in the setting of therapy resistant CACNA1A-associated hemiplegic migraine." (PMID 39110218, 2024). "Moreover, a CACNA1A variant has also been associated with migraine with aura in the last migraine association study." (PMID 36797674, 2023). "Besides the known MA-associated variant in CACNA1A, we found four other variants associating with the MA-proxy VD, all new to migraine." (PMID 37884687, 2023). "As a result, the genetic load may affect the severity and patterns of CSD, for instance, familial hemiplegic migraine (FHM1,2), a rare form of migraine with aura, was found to have a mutation in CACNA1A, ATP1A2, and the SCN1A gene, respectively." (PMID 36421543, 2022). "Articles discussed in this Review were identified by PubMed searches for the years 1990 to the present, using the search terms “migraine and calcium”, “migraine and calcium signaling”, “CACNA1A mutations”, “migraine and CaV2.1”, “migraine and glia”, “glia and calcium in migraine” among others." (PMID 33799975, 2021).
migraine (continued). "Migraine ”ionopathy” likely derives from one or multiple channelopathies which may be inherited e.g., mutations in CACNA1A and TRPA1, or result from the effects of toxic environmental factors." (PMID 33799975, 2021). "Our data suggest that CACNA1A-p.Thr501Met mutation can occur prevalently as hemiplegic migraine." (PMID 34320921, 2021). "Mutations in the CACNA1A gene result in great clinical heterogeneity, and present with chronic progressive symptoms or paroxysmal events (including sporadic and familial hemiplegic migraine (HM), epilepsy and migraine), or both." (PMID 34068417, 2021). "Our work demonstrated that deletions in CACNA1A gene may be associated also to different migraine phenotypes." (PMID 30167989, 2018). "Familial Hemiplegic Migraine type 1 (FHM-1) is a rare monogenic subtype of migraine with aura that is caused by missense mutations in the CACNA1A gene that encodes the α1 subunit of neuronal voltage-gated CaV2.1(voltage-gated calcium channel type 2.1) calcium channels." (PMID 23577145, 2013). "In addition, an analysis of about 30,000 patients from the 2022 GWAS with a precise diagnosis of the type of migraine (eg, MO or MwA) showed that three risk variants were specific for MwA (including a SNP in CACNA1A the FHM1 gene), two were specific for MO and nine were associated with both types." (PMID 36800925, 2023). "Dysregulated calcium currents as seen in the context of migraine derive largely from aberrant function of the high-voltage activated calcium channel CaV2.1 and the transient receptor potential ankyrin channel, encoded by the genes CACNA1A and TRPA1, respectively." (PMID 33799975, 2021). "It is known that the gene encodes a calcium channel that is predominantly expressed in the cerebellum and this fact may contribute to explain why familial hemiplegic migraine patients with CACNA1A mutations may frequently report central vestibular signs and symptoms." (PMID 28082766, 2016). "Mutations in CACNA1A are known to alter calcium channel function, leading to neuronal hyperexcitability and a lowered threshold for initiating CSD, a key mechanism in migraine, particularly in cases with aura." (PMID 40869402, 2025). "For instance, alterations in neurotransmitters such as glutamate and GABA; CSD; and mutations in genes including CACNA1A, ATP1A2, and SCN1A have been shown to be highly correlated with both migraine and epilepsy." (PMID 41404467, 2025). "In summary, this study enhances our understanding of the clinical course and genetic basis of migraine and underscores the potential of the CACNA1A gene as a target for future research and therapeutic development." (PMID 40869402, 2025). "Mutations in CACNA1A are directly implicated in familial hemiplegic migraine type 1 (FHM1), a rare autosomal dominant subtype of migraine." (PMID 39997646, 2025). "One patient with CACNA1A p.F1502del, a GOF variant, presented with congenital ataxia, epilepsy, GDD, abnormal eye movements, and severe hemiplegic migraines associated with hemispheric swelling." (PMID 41456028, 2025). "The CACNA gene family, particularly CACNA1A, plays a key role in a rare subtype of migraine characterized by motor aura and heightened synaptic activity, driven by increased CaV2.1 channel function, ultimately resulting in CSD." (PMID 39684844, 2024). "Some patients with HM because of CACNA1A and ATP1A2 mutations have reported developing mental retardation and cognitive disorder following migraine attacks." (PMID 38674378, 2024). "Genes such as CACNA1A, ATP1A2, and SCN1A have played an instrumental role in shaping the genetic understanding of CSD and aura mechanisms and therefore migraine susceptibility." (PMID 37628876, 2023). "Some genes such as CACNA1A, NOTCH3, TREX1 and COL4A1 are associated with nystagmus or vasculopathies related to migraines." (PMID 37622929, 2023).
migraine (continued). "The inheritance in migraine is mostly polygenic, with a few rare exceptions such as hemiplegic migraine (CACNA1A, ATP1A2, SCN1A) and cerebral autosomal dominant arteriopathy with subcortical infarcts and leukoencephalopathy (CADASIL) (NOTCH3)." (PMID 37474899, 2023). "CACNA1A (which encodes a subunit of the voltage‐gated Ca2+ channel CaV2.1) and ATP1A2 (which encodes a subunit of the Na+/K+ ATPase) are the only two genes known to cause a rare form of migraine." (PMID 35451242, 2022). "Three patients (patients 1, 2, and 3) with hemiplegic migraines were treated with intravenous corticosteroids and IVIG, as well as antiviral drugs during the acute episodes, before CACNA1A gene variants were found." (PMID 33425808, 2020). "Genetic analysis of the CACNA1A gene with direct sequencing, in a cohort of migraine sufferers (HM and MA/MO) identified 3 different point mutations." (PMID 30167989, 2018). "A part from this family, in patients with migraine (HM, MA and MO), we have detected different deletions in the 3′ end of CACNA1A." (PMID 30167989, 2018). "Familial hemiplegic migraine (FHM) is a rare, monogenic, autosomal dominant subtype of migraine, in which three genes, CACNA1A, ATP1A2, and SCN1A, are currently known to be involved." (PMID 30498473, 2018). "Two of the subjects with migraine headaches harbor variants in other genes that have previously been associated with migraine (TRAP1 and CACNA1A)." (PMID 29145497, 2017). "A recent study showed that sibling pairs with any form of migraine, especially migraine with aura, had inherited the same 19p13 CACNA1A." (PMID 25143767, 2014). "We have previously reported linkage in one large typical migraine family to the CACNA1A region on chr19." (PMID 19018300, 2008). "While pathogenic missense variants in CACNA1A, ATP1A2, and SCN1A can cause FHM or its sporadic form, they explain less than 20% of suspected hemiplegic migraine cases, suggesting the involvement of other genes or genetic variations, potentially including copy number variations (CNVs)." (PMID 42193281, 2026). "This study aimed to investigate the role of CACNA1A variants in individuals with and without a family history of migraine." (PMID 40869402, 2025). "We genotyped 150 subjects (100 migraine patients: 50 with migraine without aura (MO), 50 with migraine with aura (MA) and 50 controls) for six CACNA1A variants using Sanger sequencing." (PMID 40869402, 2025). "In terms of genetic markers, mutations in CACNA1A, ATP1A2, and SCN1A are closely associated with FHM, while variants in NOTCH3 and TREX1 genes have been linked to migraine and its associated cerebrovascular diseases (e.g., cerebral arteriolar dominant disorders)." (PMID 39958329, 2025). "This novel CACNA1A variant was absent in the control group, suggesting a potential role in migraine pathogenesis; however, further research on larger cohorts is needed to confirm this association." (PMID 40869402, 2025). "The association between familial hemiplegic migraine-related genes (CACNA1A, ATP1A2, and SCN1A) and both migraine and epilepsy, as well as the impact of polymorphisms in pain-related sodium channels SCN9A and SCN10A on migraine chronification, have been further elucidated." (PMID 41404467, 2025). "Beyond CACNA1A, other genes within the CACNA family, such as CACNA1B (encoding CaV2.2) and CACNA1E (encoding CaV2.3), have also been implicated in the pathogenesis of migraine aura." (PMID 39997646, 2025). "Non-polyglutamine CACNA1A variants underlie an extremely variable phenotypic spectrum encompassing developmental delay, hemiplegic migraine, epilepsy, psychiatric symptoms, episodic and chronic cerebellar signs." (PMID 39110218, 2024). "Interestingly, a recent genome-wide analysis of 102,084 migraine cases indicated that the CACNA1A gene is also involved in migraine with typical aura." (PMID 36627561, 2023).
migraine (continued). "More robust motor manifestations have been reported as common in migraine with sensory disturbances and unilateral weakness, and, recently, in novel forms of Familial Hemiplegic Migraine (FHM) of CACNA1A mutations with reversible unilateral or bilateral motor weakness." (PMID 35910262, 2022). "This applies to the four canonical FHM genes (CACNA1A, ATP1A2, SCN1A, and PRRT2), as well as the other genes reported to cause syndromes which may present with migraine." (PMID 36044383, 2022). "Currently, we know of the following monogenic forms of migraine: Familial hemiplegic migraine type 1 (FHM1; mutations in the calcium channel gene CACNA1A), type 2 (FHM2; mutations in the sodium/potassium-transporting ATPase gene ATP1A2) and type 3 (FHM3; mutations in the sodium channel gene SCN1A)." (PMID 35785356, 2022). "Also, persistence of slowing in the weeks after attacks appears useful to discriminate CACNA1A-related hemiplegic migraine." (PMID 33544220, 2021). "CACNA1A plays a major role in neurotransmitter release throughout the nervous system, especially in cerebellar Purkinje cells and in all brain areas involved in the pathogenesis of migraine." (PMID 34068417, 2021). "Until now, three undisputed hemiplegic migraine genes, CACNA1A (FHM1), ATP1A2 (FHM2), SCN1A (FHM3), have been identified; despite recent technical advances in whole genome/whole exon next generation sequencing no additional hemiplegic migraine genes have been identified." (PMID 34112082, 2021). "A Chinese girl and some of her relatives who presented with hemiplegia with or without migraine were found to carry a novel heterozygous missense variant, I1379F, in CACNA1A by whole-exome sequencing." (PMID 34941060, 2021). "The pleiotropic nature of CACNA1A may give rise to other phenotypic characteristics, including migraines, and hemiplegic attacks, sometimes with overlapping features in a single individual." (PMID 33833732, 2021). "Some patients with this syndrome respond to acetazolamide, but the CACNA1A pathogenic variant has not been identified in this distinct migraine population." (PMID 31640633, 2019). "However, the clinical correlation of the variants present in those subjects (TRAP1 p.Ile253Val in subject ECS031 and CACNA1A p.Ser2423_Gly2424del in subject ECS100) with migraine and anxiety is uncertain." (PMID 29145497, 2017). "For our patient #1 with CACNA1A gene mutation, he experienced three hemiplegic migraine attacks, and no mental retardation or regression manifestation has been found yet, which may be related to the patient's young age or insufficient follow-up time." (PMID 37576133, 2023). "This relationship between CACNA1A and CSD highlights the broader role of ion channel dysfunction in migraine." (PMID 40869402, 2025). "Given the considerable attention garnered by the CACNA1A gene in FHM1, emerging research suggests the potential involvement of other genes within the CACNA family in the manifestation of migraine pain." (PMID 38785745, 2024). "Phenotype similar to CACNA1A (EA2), some reported cases with seizures, migraine, alternating hemiplegia and chronic ataxia." (PMID 33833732, 2021). "Only for CACNA1A and their homolog genes (i.e., CACNA1C gene responsible for Timothy syndrome) was the coexistence between autism and migraine reported." (PMID 32899972, 2020). "Enhanced neurotransmitter release by CACNA1A mutations, excessive neuronal firing by SCN1A mutations, or impaired clearance of K+ and/or glutamate by ATP1A2 mutations can all induce cortical spreading depression (CSD), which may be the underlying pathophysiological mechanism of migraine aura." (PMID 24101904, 2013). "Several voltage-gated Ca+2 channel blockers have been developed against CACNA1A, but have not been tested in migraine." (PMID 37884687, 2023). "The CACNA1A and ATP1A2 genes have both previously been tested in the common forms of migraine, but no new mutations or the FHM mutations were detected in these MA/MO affected samples." (PMID 16162291, 2005).